ABCB4 (ATP binding cassette subfamily B member 4)
Diseases named in the same sentence as ABCB4 in open-access papers (continued):
Sharing a sentence is not in itself a finding about the gene and the disease.
breast cancer (12 papers, 2014 to 2025). A primary or metastatic malignant neoplasm involving the breast. "Curcumin reverses doxorubicin resistance via inhibiting the efflux function of ABCB4 in doxorubicin-resistant breast cancer cells." (PMID 38258090, 2024). "In a similar pattern, ABCB4 mediated the efflux transport of doxorubicin in vitro and contributed to the acquired resistance of doxorubicin in breast cancer cells." (PMID 36901890, 2023). "In a recent study, breast cancer cell lines MCF-7 and MDA-MB-231 showed increased copy numbers of ABCB1, ABCB4 (MCF-7 model), and ABCA9 (MDA-MB-231 model) to be associated with the formation of docetaxel resistance." (PMID 35631534, 2022). "The ATP-binding cassette (ABC) transporter gene ABCB4 is found to be amplified in Adriamycin-resistant breast cancer cells relative to drug-sensitive cells." (PMID 29743122, 2018). "Data from PPISURV and GOBO revealed that breast cancer patients with high expression of ABCB4 (P = 0.0242), CYP2C8 (P = 0.02028), UGT2B4 (P = 0.0181) or UGT2B17 (P = 0.00815) showed poorer survival than those with low expression." (PMID 29743122, 2018). "SPIN1 is identified as a novel target of the miR-148/152 family and enhances Adriamycin resistance by regulating drug metabolizing enzymes and transporter CYP2C8, UGT2B4, UGT2B17 and ABCB4 in breast cancer." (PMID 29743122, 2018). "A microarray-based study has shown that ABCB4 modulates the doxorubicin resistance in ovarian cells and the paclitaxel resistance in breast cancer cells." (PMID 29371412, 2018). "Altogether these data indicate that the expression of the drug metabolizing enzymes CYP2C8, UGT2B4 and UGT2B17, and transporter ABCB4 was positively regulated by SPIN1 in breast cancer." (PMID 29743122, 2018). "For breast cancer a significant tumor specific methylation of ABCB4 was found (p = 0.002, two tailed Fisher exact test)." (PMID 25367630, 2014). "Moreover, 11 out of 27 (41%) breast cancer tissues (e.g. BrCa12-T) were methylated for ABCB4." (PMID 25367630, 2014). "ABC subfamily B member 4 (ABCB4), which acts as an efflux pump to limit the intracellular accumulation of drugs, has been shown to be overexpressed in DOXO-resistant breast cancer cells." (PMID 35216255, 2022). "We find that SPIN1 increases breast cancer Adriamycin resistance via enhancing the expression of drug metabolizing enzymes and transporter CYP2C8, UGT2B4, UGT2B17 and ABCB4." (PMID 29743122, 2018). "We therefore treated the lung cancer cell lines A427, A549, H322, HCC-15, HTB171 and H1299, the breast cancer cells ZR-75-1, the HN cancer cell RPMI-2650 and the melanoma cells SK-Mel-13 with Aza or Zebu and analyzed the ABCB4 expression." (PMID 25367630, 2014). "We also observed that aberrant methylation of ABCB4 is also frequently found in primary NSCLC (39%), breast cancers (41%) and HN cancer (20%)." (PMID 25367630, 2014). "To analyze the impact of epigenetic silencing of ABCB4 in primary cancer tissues we investigated its hypermethylation in 46 primary NSCLC, 27 breast cancers and 10 HN cancers and several matching controls by COBRA." (PMID 25367630, 2014). "Also three breast cancer cell lines (MCF-7, ZR-75-1 and MDA-MB-231), three HN cancers (UM-SCC-14C, UM-SCC-22B and RPMI-2650), skin cancer C8161 and HeLa exhibited ABCB4 hypermethylation (>20%)." (PMID 25367630, 2014).
fibrosis (11 papers, 2016 to 2025). the formation of excess fibrous connective tissue in an organ or tissue in a reparative or reactive process. "The gain of periportal and septal fibrosis characterized progressive fibrosis in Abcb4−/−/HBsAg+/− mice." (PMID 28881751, 2017). "While liver fibrosis induced by TAA or CCl4 is mainly pericentral, fibrosis in Abcb4−/− mice is restricted to periportal areas." (PMID 40635671, 2025).
liver cirrhosis (11 papers, 2014 to 2025). "A 55-year-old male Caucasian patient presenting with low phospholipid-associated cholelithiasis syndrome with ATP-binding cassette subfamily B member 4 mutation and liver cirrhosis was referred to our clinic for a liver transplant." (PMID 38135884, 2023). "Subsequently, we compared the distribution of ABCB4 variant in patients with and without liver cirrhosis separately for the PBC and PSC." (PMID 36397154, 2022).
progressive familial intrahepatic cholestasis (11 papers, 2015 to 2025). Progressive familial intrahepatic cholestasis (PFIC) refers to a heterogeneous group of autosomal recessive disorders of childhood that disrupt bile formation and present with cholestasis of hepatocellular origin. "Progressive familial intrahepatic cholestasis (PFIC) type 3 is an autosomal recessive disorder arising from mutations in the ATP-binding cassette subfamily B member 4 (ABCB4) gene." (PMID 33256620, 2020). "Hereditary cholestatic syndromes in children, clinically presenting as progressive familial intrahepatic cholestasis (PFIC) types 1–3, result from mutations of ATP8B1, ABCB11, and ABCB4." (PMID 28626473, 2017). "Genetic testing should also be considered such as mutations in the hepatobiliary transporters ATP8B1, ABCB11 and ABCB4 in the evaluation of familial hepatocellular cholestasis like progressive familial intrahepatic cholestasis (PFIC) or benign recurrent intrahepatic cholestasis (BRIC)." (PMID 39600379, 2023).
cholangiocarcinoma (9 papers, 2014 to 2025). A carcinoma that arises from the intrahepatic biliary tree (intrahepatic cholangiocarcinoma) or from the junction, or adjacent to the junction, of the right and left hepatic ducts (hilar cholangiocarcinoma). "Three cases of cholangiocarcinoma were observed during the follow-up in our study, all cases being occurred in individuals with macrolithiasis cholangiopathy and ABCB4 mutation." (PMID 36277956, 2022). "All these 3 cases were mass-forming cholangiocarcinoma developed in symptomatic intrahepatic macrolithiasis cholangiopathy in individuals with an ABCB4 variant." (PMID 36277956, 2022). "The association between cholangiocarcinoma, a rare malignant tumor of the biliary tract, and ABCB4 mutations has been recently reported." (PMID 25133187, 2014).
Alagille syndrome (7 papers, 2020 to 2024). "Could single-gene analysis for JAG1, NOTCH2 (Alagille syndrome), SERPINA 1(A1ATd), DCDC2 (isolated neonatal sclerosing cholangitis), and ABCB4 (PFIC3) still be used to exclude these intrahepatic diseases and avoid diagnostic errors in the first step of the investigation?" (PMID 36292464, 2022).
cystic fibrosis (7 papers, 2013 to 2025). Autosomal recessive disorder caused by pathogenic variants in the CFTR gene (cystic fibrosis transmembrane conductance regulator), which encodes a chloride and bicarbonate channel expressed in epithelial cells, and follow the diagnosis criteria. "In the same manner, the newly identified compounds may be combined with potentiators, as performed for cystic fibrosis patients carrying the F508del mutation, since the potentiator VX-770/ivacaftor has been shown to partially correct the function of activity-defective class III ABCB4 variants." (PMID 39048674, 2024).
biliary atresia (6 papers, 2020 to 2025). A rare, biliary tract disease characterized by progressive obliterative cholangiopathy of the intra- and extrahepatic bile ducts, occurring in the embryonic/ perinatal period, leading to severe and persistent neonatal jaundice and acholic stool. "Similarly, as confirmed in this study, early in the course of biliary atresia in infants, most canalicular transporters are downregulated, including bile salt export pump (BSEP, ABCB11), multidrug-resistant protein 3 (MDR3, ABCB4), and the multidrug-resistant associated protein 2 (MRP2, ABCC2)." (PMID 34774795, 2021). "Notably, ABCG2 and ABCC4 are almost absent in controls but abundant in biliary atresia; ABCB1 and ABCB4 are both significantly upregulated to the point that ABCB4 is the most abundant transporter in BA Livers, overtaking ABCD3." (PMID 33128234, 2020).
liver failure (6 papers, 2020 to 2026). A liver disease characterized by the liver losing or has lost all of its function. "In our study, the patient with MDR3 deficiency presented with a homozygous mutation in the ABCB4 gene, and mutations in both alleles might have caused rapid liver failure in early childhood." (PMID 35024979, 2022).
liver inflammation (6 papers, 2014 to 2024). "100% of aging Abcb4−/− mice display metabolic derangement due to liver inflammation and toxicity induced by a progressive increase and accumulation of BAs." (PMID 30464200, 2018).
melanoma (6 papers, 2010 to 2024). A malignant, usually aggressive tumor composed of atypical, neoplastic melanocytes. "Analysis of RNA expression data from all 78 melanoma cell lines available on the DepMap portal revealed a wide range of gene expression of the three efflux transporters of interest with MDR3 (ABCB4) most highly expressed." (PMID 38226983, 2024). "Thus, it will be interesting to analyze the methylation status of ABCB4 in primary melanomas." (PMID 25367630, 2014). "Gene expression analysis based upon CCLE data, showed a number of the melanoma cell lines express ABCB1, ABCB4 and ABCG2 transcripts, however levels varied widely." (PMID 38226983, 2024). "This analysis showed variable RNA expression of the three efflux transporter genes ABCB1 (P-gp), ABCB4 (MDR3) and ABCG2 (BCRP) across the melanoma cell line panel." (PMID 38226983, 2024).
Wilson disease (6 papers, 2021 to 2025). A very rare inherited multisystemic disease presenting non-specific neurological, hepatic, psychiatric or osseo-muscular manifestations due to excessive copper deposition in the body. "For inherited diseases such as PFIC1, PFIC2, PFIC3, and Wilson’s disease, the coding regions of the ATP8B1, ABCB11, ABCB4, and ATP7B sequences exceed the AAV vector capacity." (PMID 39684224, 2024).
colitis (5 papers, 2016 to 2024). Inflammation of the colon. "To further confirm the protection displayed by Abcb4−/− mice against intestinal tumorigenesis, we challenged mice with a complementary experimental setting, the azoxymethane-Dextran sulfate sodium (AOM/DSS) colitis-carcinogenesis model." (PMID 27995969, 2016). "In fact, mRNA levels of Tumor Necrosis Factor-α (Tnfα) and Interleukin-1β (data not shown) were even increased in the colon mucosa of Abcb4−/− mice, further ruling out the hypothesis that reduced inflammation can be the mechanism of protection in the colitis carcinogenesis model." (PMID 27995969, 2016).
colon carcinoma (5 papers, 2016 to 2023). "Abcb4−/− mice fed the PC diet lost the protection against AOM/DSS, displaying colon tumor number and size similar to that of Abcb4+/+ mice." (PMID 27995969, 2016). "In addition, ABCB4 could function as a tumour suppressor gene in CRC, as evidenced by the finding that 5-FU-resistant colon cancer cells exhibit downregulation of the ABCB4 gene." (PMID 36674859, 2023). "Compared to littermate controls, Abcb4−/− mice challenged with AOM/DSS developed fewer and smaller colonic tumors." (PMID 27995969, 2016).
Hepatic steatosis (5 papers, 2020 to 2025). Steatosis is a term used to denote lipid accumulation within hepatocytes. "4/6 (66.6%) of cases with hepatic steatosis had an ABCB4 LoF and 2/6 (33.3%) had an ABCB11 LoF or SNV." (PMID 41436587, 2025). "Pathogenic variants were detected in the ABCB4 gene in a patient with idiopathic cholestasis, in the APOB and CP genes in a patient with hepatic steatosis, in the ABCB4 gene in a patient with elevated liver enzymes, and in the MTTP and AGL genes in a patient with cryptogenic cirrhosis." (PMID 40870862, 2025).
ovarian carcinoma (5 papers, 2012 to 2021). A malignant neoplasm originating from the surface ovarian epithelium. "Furthermore, ABCB4 (MDR3) is also linked with chemotherapy resistance and is increased in recurrent ovarian cancers." (PMID 34504843, 2021). "Among the various ABC transporters, ABCB1 (MDR1) and ABCB4 (MDR3) are thought to play important roles in ovarian cancer." (PMID 34504843, 2021). "ABCB4 was up-regulated 176-fold in doxorubicin- and 147-fold in vincristine-resistant sublines of ovarian cancer cells which proves that ABCB4 does contribute to chemotherapy resistance just like ABCB1." (PMID 28119610, 2016). "However, the exact role of ABCB4transporter in MDR is still unclear, as silencing of ABCB4 did notrestore sensitivity whereas silencing of ABCB1 completely restoredsensitivity in taxane-resistant ovarian cancer cell line." (PMID 31223218, 2018). "Reversal of MDR in ovarian cancer cell lines is possible with siRNA knockout of ABCB1 (MDR1) and ABCB4 (MDR3) genes, combination drug treatments, chitosan/pshRNA plasmid nanoparticle targeting of MDR1 genes, and perturbation of P-glycoprotein N-glycosylation." (PMID 22481932, 2012).
Jaundice (4 papers, 2011 to 2024). Yellow pigmentation of the skin due to bilirubin, which in turn is the result of increased bilirubin concentration in the bloodstream. "The two whose bilirubin concentrations were consistent with jaundice (>35 μmol/L) harboured ABCB4 mutations." (PMID 28924228, 2017).
Low phospholipid-associated cholelithiasis (4 papers, 2014 to 2025). "Low phospholipid-associated cholelithiasis (LPAC) syndrome is a rare condition that is caused by ABCB4/MDR3 mutation." (PMID 38940909, 2025). "Low phospholipid-associated cholelithiasis (LPAC) syndrome is a rare biliary disorder caused by mutations in the ABCB4 gene, which encodes the MDR3 phosphatidylcholine transporter." (PMID 40499451, 2025).
lung carcinoma (4 papers, 2014 to 2025). "The direct evidence have shown that loss of ABCB4 promotes the proliferation in the lung cancer." (PMID 29371412, 2018). "Given that the human dynamic scans for this radiotracer are reported in lung cancer, the ABCB4-rich PC-9 human non-small cell lung cancer (NSCLC) xenograft model was used." (PMID 34452207, 2021). "To verify the ability of ABCB4 to suppress tumor growth like, we performed colony formation and proliferation assays in lung cancer cell lines." (PMID 25367630, 2014). "Overexpression of ABCB4 significantly suppressed colony formation and proliferation of lung cancer cells." (PMID 25367630, 2014). "Aberrant methylation of ABCB4 was also revealed in 39% of primary lung cancer and in 20% of head and neck cancer tissues." (PMID 25367630, 2014). "Our findings suggest that ABCB4 is a frequently silenced gene in different cancers and it may act tumor suppressivly in lung cancer." (PMID 25367630, 2014). "Aza treatment of the lung cancer cells H1299 lead to ABCB4 reexpression on protein level." (PMID 25367630, 2014). "Interestingly, we also observed a growth suppressive function of ABCB4 in lung cancer cells." (PMID 25367630, 2014). "Furthermore, ectopic expression of ABCB4 suppresses colony formation in lung cancer cells." (PMID 25367630, 2014). "Furthermore, RACK1 is a regulatory cofactor of the phosphatidylcholine translocator ABCB4, which is also induced by CBD and has been reported to suppress colony formation and proliferation of lung cancer cells." (PMID 40429863, 2025). "Expression of ABCB4 was also analyzed on a lung cancer tissue array (data not shown)." (PMID 25367630, 2014). "In 37% of primary lung cancer samples, ABCB4 expression was absent." (PMID 25367630, 2014).
Wilms tumor (4 papers, 2017 to 2023). An embryonal neoplasm characterized by the presence of epithelial, mesenchymal, and blastema components. "ABCB4 overexpression was also correlated with high-risk Wilms tumors." (PMID 36901890, 2023). "Previous reports showed that ABCB4 and ABCC1 overexpression correlates with high-risk and significantly shorter disease-free survival time in patients with Wilms tumors (WT)." (PMID 36901890, 2023).
colorectal cancer (3 papers, 2017 to 2026). A primary or metastatic malignant neoplasm that affects the colon or rectum. "In addition to the molecular researches, a population-based research showed lower transcript level of ABCB4 in accordance with a shorter disease-free interval in colorectal cancer patients treated by adjuvant chemotherapy." (PMID 29371412, 2018). "ABCB4 may serve as a clinical marker in colorectal cancer patients." (PMID 29371412, 2018). "However, the involvement of ABCB4 in colorectal cancer resistance remains to be illustrated." (PMID 29371412, 2018). "Although ABCB4 shares some similarity with ABCB1, the ABCB4 showed a different pattern in the colorectal cancer." (PMID 29371412, 2018).
glioma (3 papers, 1997 to 2024). A benign or malignant brain and spinal cord tumor that arises from glial cells (astrocytes, oligodendrocytes, ependymal cells). "Next, using a biological database and clinical glioma samples, we found that ABCB4 is highly expressed in GBM, and that ABCB4 overexpression is highly correlated with poor prognosis in patients with GBM." (PMID 38710703, 2024). "Our study found that GSCs can also transmit their highly expressed ABCB4 to differentiated glioma cells (DGCs) through exosomes, leading to high expression of ABCB4 in these cells and promoting their resistance to TMZ." (PMID 38710703, 2024). "We also found that GSCs can transfer ABCB4 to differentiated glioma cells (DGCs) through exosomes, thus promoting DGC resistance to TMZ." (PMID 38710703, 2024). "Notably, ABCB4 exhibited consistent behaviour across all three datasets, suggesting a potentially widespread and significant biological role in glioma resistance." (PMID 38710703, 2024). "However, the biological role of ABCB4 in glioma has seldom been reported." (PMID 38710703, 2024).
leukaemia (3 papers, 2020 to 2025). "In leukaemia cells, daunorubicin accumulation is dependent on transporter inhibition with Cyclosporin A, indicating that ABCB4 is able to remove ABCB1 substrates from cancer cells and may play an active role in drug resistance." (PMID 36901890, 2023). "High levels of ABCB4 expression have been reported in different leukaemias, even without co-expression with ABCB1." (PMID 36901890, 2023).
medulloblastoma (3 papers, 2013 to 2023). A malignant, invasive embryonal neoplasm arising from the cerebellum. "In the pediatric medulloblastoma, high expression of ABCB4 links to the radiation resistance." (PMID 29371412, 2018).
alexithymia (2 papers, 2023 to 2024). An agnosia that is a deficiency in understanding, processing, or describing emotions. "The exome association analysis detected four significant variants (ABCB4 gene: rs45575636, TP53AIP1 gene: rs35942033, ARHGAP32 gene: rs35287114, and TMEM88B gene: rs144957058) associated with alexithymia." (PMID 39202385, 2024). "Little GWAS data are currently available on alexithymia and emotional dysregulation; more research is needed in this area, as the data currently available already yielded some interesting results (TMEM88B, ABCB4 and TP53AIP1 for alexithymia, and ILR2A for emotional dysregulation)." (PMID 36729042, 2023).
atrial fibrillation (2 papers, 2015 to 2024). A disorder characterized by an electrocardiographic finding of a supraventricular arrhythmia characterized by the replacement of consistent P waves by rapid oscillations or fibrillatory waves that vary in size, shape and timing and are accompanied by an irregular ventricular response. "With respect to the rest of the cohort, individuals with the Thr175Ala amino acid change in ABCB4 have a 3.75-fold increase in the probability of developing atrial fibrillation/flutter." (PMID 25888430, 2015).
diabetes (2 papers, 2013 to 2021). "Interestingly, ABCB4 is also implicated in glucose metabolism, and GSLs play a key role in diabetes." (PMID 34597626, 2021).